ZNF787 (zinc finger protein 787)
Description:
May be involved in transcriptional regulation.
Synonyms: TIP20
Tractability: PROTAC: UniProt records ubiquitination sites on it; its protein half-life has been measured.
Target class: Transcription factor
Gene: Protein-coding gene on chromosome 19 (56,087,366 to 56,121,295, reverse strand). Ensembl gene ENSG00000142409.
Subcellular location: Nucleus
Subcellular location (Human Protein Atlas): Nucleoplasm; Mitochondria; Nucleoli
Gene Ontology:
Molecular function: sequence-specific double-stranded DNA binding; DNA-binding transcription factor activity, RNA polymerase II-specific; sequence-specific DNA binding
Biological process: regulation of transcription by RNA polymerase II
Cellular component: nucleus
Genetic constraint (gnomAD): Loss-of-function variants: 10 observed, 13.97 expected, observed/expected ratio (o/e) 0.72, 90% interval 0.44 to 1.21. The synonymous counts are far from expectation, so gnomAD's model fits this gene poorly and the ratio says little. Missense variants: 515 observed, 409.98 expected, observed/expected ratio (o/e) 1.26, 90% interval 1.17 to 1.35. Synonymous variants: 326 observed, 211.57 expected, observed/expected ratio (o/e) 1.54, 90% interval 1.41 to 1.69.
Homologues: Orthologues: macaque ZNF787 (99% identical), dog ZNF787 (96% identical), pig ZNF787 (96% identical), mouse Zfp787 (93% identical), guinea pig ZNF787 (88% identical), rat Zfp787 (85% identical). Paralogues in human: ZNF316 (38% identical).
Diseases named in the same sentence as ZNF787 in open-access papers:
ZNF787 is named in the same sentence as 1 disease in open-access papers, as found by Europe PMC text mining. Sharing a sentence is not in itself a finding about the gene and the disease.
ZNF787 shares sentences with these, for which no sentence is quoted: tumours (1 paper).